BZW2 (basic leucine zipper and W2 domains 2)
Description:
Translation initiation regulator which represses non-AUG initiated translation and repeat-associated non-AUG (RAN) initiated translation by acting as a competitive inhibitor of eukaryotic translation initiation factor 5 (EIF5) function. Increases the accuracy of translation initiation by impeding EIF5-dependent translation from non-AUG codons by competing with it for interaction with EIF2S2 within the 43S pre-initiation complex (PIC) in an EIF3C-binding dependent manner.
Synonyms: 5MP1; HSPC028; MSTP017; MST017
Tractability: Antibody: the Human Protein Atlas places it where antibodies can reach. PROTAC: ubiquitination databases record sites on it; its protein half-life has been measured.
Gene: Protein-coding gene on chromosome 7 (16,644,653 to 16,706,771, forward strand). Ensembl gene ENSG00000136261.
Subcellular location: Cytoplasm
Subcellular location (Human Protein Atlas): Actin filaments; Cytosol; Plasma membrane
Gene Ontology:
Molecular function: cadherin binding; protein binding
Biological process: regulation of translational initiation
Cellular component: cytoplasm; membrane
Genetic constraint (gnomAD): Loss-of-function variants: 19 observed, 46.71 expected, observed/expected ratio (o/e) 0.41, 90% interval 0.28 to 0.6. The upper end of that interval is the gene's LOEUF score, 0.6, which puts it in group 2 of 6, group 1 being the genes least tolerant of losing a copy. Missense variants: 390 observed, 473.14 expected, observed/expected ratio (o/e) 0.82, 90% interval 0.76 to 0.9. Synonymous variants: 216 observed, 176.43 expected, observed/expected ratio (o/e) 1.22, 90% interval 1.1 to 1.37.
Homologues: Orthologues: chimpanzee BZW2 (100% identical), dog BZW2 (100% identical), macaque BZW2 (100% identical), mouse Bzw2 (99% identical), rat Bzw2 (99% identical), pig BZW2 (96% identical), rabbit BZW2 (95% identical), guinea pig BZW2 (89% identical), zebrafish bzw2 (84% identical), tropical clawed frog bzw2 (84% identical), Drosophila melanogaster kra (50% identical). Paralogues in human: BZW1 (72% identical).
Diseases named in the same sentence as BZW2 in open-access papers:
BZW2 is named in the same sentence as 21 diseases in open-access papers, as found by Europe PMC text mining. Sharing a sentence is not in itself a finding about the gene and the disease. The quoted sentences say what the papers report.
hepatocellular carcinoma (6 papers, 2020 to 2024). A malignant tumor that arises from hepatocytes. "BZW2 has been reported to be implicated in different types of cancers, such as colorectal cancer, muscle-invasive bladder cancer, hepatocellular cancer and osteosarcoma." (PMID 38424042, 2024). "More recently, overexpression of BZW2 has been identified to be associated with hepatoma cell drug resistance, and inhibition of BZW2 inhibits cell proliferation, migration, and invasion by regulating PI3K/Akt/mTOR signaling pathway." (PMID 33005104, 2020). "In hepatocellular carcinoma and osteosarcoma, BZW2 enhances the malignant progression of tumors by the phosphoinositide 3-kinase/protein kinase B signaling pathway." (PMID 38424042, 2024). "BZW2 participates in the development of multiple types of cancer, such as hepatocellular carcinoma, colorectal cancer, and bladder cancer." (PMID 36473368, 2023). "Furthermore, let-7a-5p can decrease BZW2 expression, and it inhibits hepatoma cell proliferation, invasion, and migration and increases apoptosis." (PMID 38255968, 2024). "However, little is known about the role of BZW2 in hepatocellular carcinoma (HCC)." (PMID 34335929, 2021).
colorectal cancer (5 papers, 2019 to 2024). A primary or metastatic malignant neoplasm that affects the colon or rectum. "In colorectal cancer, BZW2 promotes cell growth and metastasis by specifically activating the extracellular-signal-regulated kinase/mitogen-activated protein kinase signaling pathway." (PMID 38424042, 2024). "It was reported that BZW2 acts as an oncogenic driver gene and controls the selection of translational start codons of the c-Myc oncogene in colorectal cancer." (PMID 34335929, 2021). "Using a bioinformatics approach, we identified translation initiation regulator 5MP1/BZW2 on chromosome 7p as a potential oncogenic driver gene in colorectal cancer (CRC), and explored the biological effect of 5MP1 in CRC in vitro or in vivo." (PMID 31175057, 2019).
lung adenocarcinoma (5 papers, 2021 to 2025). A carcinoma that arises from the lung and is characterized by the presence of malignant glandular epithelial cells. "In lung adenocarcinoma, BZW2 promotes tumor malignant progression by enhancing the ubiquitination and degradation of GSK3β." (PMID 40413536, 2025). "In vitro and in vivo studies verified that BZW2 facilitated the malignant progression of lung adenocarcinoma by governing IDH3G expression through glycolysis-mediated histone lactylation." (PMID 39502530, 2024). "The role of Basic leucine zipper and W2 domains 2 (BZW2) in the advancement of different types of tumors is noteworthy, but its involvement and molecular mechanisms in lung adenocarcinoma (LUAD) remain uncertain." (PMID 38424042, 2024). "BZW2 (basic leucine zipper and W2 domains 2) overexpression in lung adenocarcinoma has been related to tumor size, stage, and lymphatic invasion." (PMID 36661515, 2023). "BZW2 expression has been shown to be of prognostic significance in patients with lung adenocarcinoma." (PMID 34696677, 2021).
osteosarcoma (5 papers, 2019 to 2024). A usually aggressive malignant bone-forming mesenchymal neoplasm, predominantly affecting adolescents and young adults. "Silencing of BZW2 retarded cell growth in osteosarcoma through regulating the Akt/mTOR signaling pathway." (PMID 36473368, 2023). "Cheng and colleagues have reported that suppression of BZW2 exists inhibitory effects on osteosarcoma growth in part by the regulation of the Akt/mTOR signaling pathway." (PMID 33005104, 2020). "Another study performed by Cheng and colleagues also suggested that suppression of BZW2 had inhibitory effects on osteosarcoma growth in part by the regulation of the Akt/mTOR signaling pathway." (PMID 33005104, 2020). "Recently, BZW2 has been recognized to be involved in the osteosarcoma by the regulation of Akt/mTOR signaling pathway." (PMID 33005104, 2020).
bladder cancer (4 papers, 2019 to 2025). "The knockout of BZW2 in bladder cancer cells blocked cell cycle progression and apoptosis induction." (PMID 40070829, 2025). "More recently, Gao and colleagues revealed that the knockdown of BZW2 suppresses cell growth, G1 arrest and apoptosis in the muscle‐invasive bladder cancers." (PMID 33005104, 2020). "We evaluated the expression level of BZW2 in clinical patients with advanced bladder cancer (of stage T2 and above), as well as in two different human MIBC cell lines (5637 and T24)." (PMID 30932331, 2019).
lung carcinoma (4 papers, 2019 to 2024). "The KM plot analysis showed that the overregulation of three oncogenes (SOX4, BZW2, and FOXM1) as well the downregulation of four tumor suppressors (SOX17, ZBTB16, TAL1, and KLF4) is associated with worse overall survival (OS) for lung cancer patients." (PMID 36661515, 2023). "Therefore, BZW2 overexpression suggests that it is an oncogene in lung cancer related to the phosphorylation of the components of the AKT/mTOR pathway." (PMID 36661515, 2023). "The seven top deregulated transcription factors (SOX4, SOX17, BZW2, FOXM1, ZBTB16, TAL1, and KLF4) consistently appear to be co-expressed with other frequent DEGs and transcription factors throughout the analysis in lung cancer and PAH." (PMID 36661515, 2023). "ZNF3 and BZW2 have not been previously related with IBD pathogenesis, and both were identified as common overregulated genes in colon and lung cancer, respectively, suggesting their importance in the establishment of tumoral processes." (PMID 39791702, 2024).
laryngeal papilloma (3 papers, 2020 to 2023). "In laryngeal papilloma, LINC00174 enhanced the proliferation and apoptosis evasion of laryngeal papilloma cells by regulating miR-4500/BZW2 axis." (PMID 34226413, 2021). "We observed the levels of BZW2 were up-regulated in the laryngeal papilloma (LP) tissues as compared with adjacent tissues." (PMID 33005104, 2020).
fibrosarcoma (2 papers, 2022 to 2025). A malignant mesenchymal fibroblastic neoplasm affecting the soft tissue and bone. "In fibrosarcoma, BZW2 can promote tumor growth, and it is also expressed at high levels in colorectal and liver cancers." (PMID 40070829, 2025).
melanoma (2 papers, 2019 to 2020). A malignant, usually aggressive tumor composed of atypical, neoplastic melanocytes. "Previous studies have demonstrated that high expressions of BZW2 in a series of cancers including pancreatic cancer, urothelial cancer, thyroid cancer, and melanoma." (PMID 33005104, 2020). "Additionally, high expressions of BZW2 also been identified in pancreatic cancer, urothelial cancer, thyroid cancer, and melanoma." (PMID 33005104, 2020).
lymphoma (1 paper, 2008). A malignant (clonal) proliferation of B- lymphocytes or T- lymphocytes which involves the lymph nodes, bone marrow and/or extranodal sites. "Genes whose expression was “high” in more than 95% of human lymphomas, whose gene names include: BZW2, H2AFY, SFRS3, NAP1L1, NOLA2, UBE2D2 and CCNG1 (p = 4.07×10−5)." (PMID 18535662, 2008).
osteoarthritis (1 paper, 2021). A noninflammatory degenerative joint disease occurring chiefly in older persons, characterized by degeneration of the articular cartilage, hypertrophy of bone at the margins and changes in the synovial membrane. "Among them, Ribosomal proteins were upregulated in the synovial membranes of female patients with Osteoarthritis, Carhsp1 can regulate the stability of TNF -α mRNA, they might be associated with RA, no other proteins, such as Wars, Yars, Bzw2, Mcts1 and Eif4b were reported in RA." (PMID 35006449, 2021).
tumor (15 papers, 2019 to 2025). "BZW1 and BZW2 expression were positively associated with T cell mediated immune response to tumor cell and Th2 cells in xCell database." (PMID 36267402, 2022). "BZW1 and BZW2 expression are positively associated with T cell mediated immune response to tumor cell and Th2 cells in PAAD." (PMID 36267402, 2022). "The oncogenic properties of BZW2 are associated with the translation of ATF4, another transcription factor, delaying the restart and thus promoting the survival of stress-exposed tumor cells." (PMID 40070829, 2025). "We used HE staining to evaluate tumor morphology and IHC analysis to evaluate BZW2 expression, Ki67 expression and PCNA expression." (PMID 38424042, 2024). "Altogether, these findings suggested that BZW2 served as a tumor stimulator to promote the proliferation, migration and invasion of LUAD cells in vitro." (PMID 38424042, 2024). "In addition, the results of correlation analysis suggested that BZW1 and BZW2 expression was negatively associated with neutrophil activation involved in the immune response but positively correlated with T cell mediated immune response to tumor cells (Ps < 0.05)." (PMID 36267402, 2022). "All the results indicated that BZW2 is significantly more upregulated in tumor tissues than in adjacent tissues." (PMID 34335929, 2021). "For instance, BZW2 expression is higher in the tumor tissues of muscle-invasive bladder cancers than in normal tissues." (PMID 34335929, 2021). "To this end, we performed in vivo studies to assess the effect of BZW2 knockdown on the tumour growth in mice xenograft model." (PMID 30932331, 2019). "From our results, it was obvious that BZW2‐knockdown significantly reduced the tumour volume in vivo." (PMID 30932331, 2019). "We also assessed the effects of BZW2 knockdown on cell growth, cell cycle progression, cell death in vitro, as well as the tumour growth inhibition in vivo." (PMID 30932331, 2019). "Furthermore, expression of BZW2 positively correlates with T cell-mediated immunity to tumor cells and Th2 cells, and THBS1 can reduce the permeability of human dermal microvascular endothelial cells (HDMECs)." (PMID 37122373, 2023). "Moreover, down-regulated expression of BZW2 in tumor tissue was detected among KIRC, THCA and KICH (Ps)." (PMID 36267402, 2022). "In this study, we confirmed that BZW2 and c-Myc expression was positively correlated and that BZW2 upregulation increased the expression of c-Myc, suggesting that BZW2 might modulate tumor cell growth in HCC by regulating the c-Myc pathway." (PMID 34335929, 2021). "Accumulating evidence has gradually determined the role of BZW2 in tumor biology." (PMID 34335929, 2021). "Clinically, BZW2 expression was higher in MIBC tissues than the adjacent non‐tumour tissues." (PMID 30932331, 2019). "The tumour proliferation was significantly inhibited in the BZW2 knock down mice." (PMID 30932331, 2019). "The in vivo studies with xenograft mice models validated our assertion that BZW2 could serve as an effective anti‐cancer target against MIBCs, which was evidenced by the observations that BZW2 knockdown significantly inhibited the tumour growth." (PMID 30932331, 2019). "KPNA2, BZW2 and KIF15 were involved in protein synthesis and transport and were suggested to be related to tumor progression." (PMID 37202800, 2023). "Tumor Immune Single-Cell Hub (TISCH) analyses indicated that BZW1 and BZW2 were mainly expressed in B cells and malignant cells." (PMID 36267402, 2022). "Given that morphological plasticity is a key determinant of cell migration, many of the identified genes were found to have a role in promotion of tumor cell migration and invasion, including ECM production and mesenchymal state induction (HEG1, BZW2, DCAF13, SQLE, PKIA)." (PMID 35879361, 2023). "Hence, these genes might serve as molecular targets to restrict oncogenic (i.e. ATIC, BZW2) and lipogenic (i.e. CD36, PPARγ), but promote tumor suppressive (i.e. TAGLN2) activity to treat human HCC." (PMID 32559205, 2020).
cancer (13 papers, 2019 to 2025). A tumor composed of atypical neoplastic, often pleomorphic cells that invade other tissues. "The present investigation offers crucial proof of the cancer-causing role of BZW2 in vitro and in vivo, while also explaining the underlying mechanism in LUAD." (PMID 38424042, 2024). "To explore the possible molecular mechanism underlying the anti‐cancer effects of BZW2 in MIBCs, we performed microarray pathway analysis of the signalling and disease states which might be affected by the knockdown of BZW2." (PMID 30932331, 2019). "The dysregulation of BZW2 may thus be a hallmark of certain forms of cancer." (PMID 40070829, 2025). "Accumulating evidence suggests that BZW2 is an oncogene and promotes the progression of various kinds of cancers." (PMID 38424042, 2024). "According to the TCGA database, BZW2 is highly expressed in many different types of cancers, including LUAD, liver hepatocellular carcinoma and so on." (PMID 38424042, 2024). "Its oncogenic role is beginning to emerge with reports of BZW2 promoting a variety of cancers including acute myeloid leukemia, multiple myeloma, throat, bone, bladder, colorectal, pancreatic, and liver cancer." (PMID 38154691, 2023). "Despite reports of basic leucine zipper and W2 domain-containing protein 2 (BZW2) promoting cancer progression first emerging in 2017, little is known about its molecular function." (PMID 38154691, 2023). "And down-regulated expression of BZW2 was detected among 6 types of carcinomas, including KIRP, KIPAN, TGCT, PCPG, ACC and KICH (Ps < 0.05)." (PMID 36267402, 2022). "Both ATIC and BZW2 are considered human oncogenic genes that promote cancer proliferation and migration through mTOR signaling." (PMID 32559205, 2020). "To identify the roles of the expression of BZW family members (BZW1 and BZW2) in cancer patients, we screened comprehensive datasets and found the corresponding hazard ratios and p-values from in silico analysis." (PMID 31601833, 2019). "Besides, other identified cancer‐associated functions and states include cell death and survival, cellular development, cellular growth and proliferation, cell morphology, cellular assembly and organization and cellular movement, implying the important role of BZW2 in the tumorigenesis of MIBCs." (PMID 30932331, 2019). "Evidence from previous studies indicates that BZW2 is involved in tumorigenesis in several cancers." (PMID 34335929, 2021). "All these results suggested BZW2 as a potential target for some types of cancer." (PMID 33005104, 2020). "Many recent studies had shed light on the roles of BZW2 in cancers." (PMID 33005104, 2020). "In fact, the pro-oncogenic properties of BZW2 have been associated with the translation of the transcription factor ATF4 through the process whereby reinitiation is delayed based on upstream open reading frames 5, thereby enhancing the survival of cancer cells under stress conditions." (PMID 34335929, 2021). "Our results suggested that BZW2 could serve as a potential anti‐cancer target against MIBCs." (PMID 30932331, 2019). "We performed immunohistochemical analysis of ACAT2, SPHK1, SNED1, KPNA2, BZW2 and KIF15 in cancer and normal tissues and statistically analyzed the staining intensity." (PMID 37202800, 2023). "BZW2 and CCT2 have been shown to promote the proliferation of various tumors and affect the prognosis of cancer." (PMID 34696677, 2021).
adenocarcinoma (1 paper, 2019). A common cancer characterized by the presence of malignant glandular cells. "In addition, BZW2 did not have a significant clinicopathological value in either adenocarcinoma or the squamous subtype." (PMID 31601833, 2019).
BZW2 also shares sentences with these, for which no sentence is quoted: colorectal adenoma (1 paper); liver cancer (1); mucosal (1); nasopharyngeal carcinoma (1); neurodevelopmental disorder (1); pancreatic cancer (1); thyroid cancer (1).